SMARCA4 (SWI/SNF related BAF chromatin remodeling complex subunit ATPase 4)
Diseases named in the same sentence as SMARCA4 in open-access papers (continued):
Sharing a sentence is not in itself a finding about the gene and the disease.
thoracic tumors (continued). "Additionally, targeted therapies involving Enhancer of Zeste Homolog 2 (EZH2) inhibitors and histone deacetylase (HDAC) inhibitors have shown promising therapeutic potential in SMARCA4-deficient undifferentiated thoracic tumors." (PMID 41312169, 2025). "Given the morphological and molecular similarities between SMARCA4-deficient thoracic tumors and U-CUP, we hypothesized that SMARCA4 deficiency may similarly predict ICI efficacy in CUP." (PMID 40866717, 2025). "Clinical features of cases with SMARCA4 deficient undifferentiated thoracic tumor." (PMID 40909976, 2025). "Here, illustrating the challenges highlighted by a real-world case, we describe the diagnostic pathway leading to SMARCA4-UT identification and discuss the differential diagnosis of thoracic tumors, relevant molecular evaluations, the molecular basis of SMARCA4-UT, and treatment implications." (PMID 40421964, 2025). "SMARCA4-deficient undifferentiated thoracic tumors are a rare phenomenon." (PMID 38390699, 2024). "SMARCA4-deficient undifferentiated thoracic tumor is extremely invasive." (PMID 38347129, 2024). "Therefore, it was once proposed as a new type of thoracic tumor and named SMARCA4-deficient thoracic sarcoma (SMARCA4-DTS)." (PMID 38347129, 2024). "In this study, we evaluated the clinicopathological, immunohistochemical, and genetic characteristics of 36 patients with advanced SMARCA4‐deficient thoracic tumors, consisting of 21 SMARCA4‐NSCLCs and 15 SMARAC4‐UTs, and analyzed responses to platinum‐based chemotherapy and PD‐1 inhibitors." (PMID 38124509, 2023). "The clinicopathological characteristics of patients with SMARCA4‐deficient thoracic tumors." (PMID 38124509, 2023). "The efficacy of PD‐1 inhibitors in treating SMARCA4‐deficient thoracic tumors remains uncertain." (PMID 38124509, 2023). "PD‐1 inhibitors showed promising efficacy in treating advanced SMARCA4‐deficient thoracic tumors." (PMID 38124509, 2023). "Therefore, these two types of thoracic tumors harboring loss of SMARCA4 should be viewed as two related but different entity." (PMID 37115272, 2023). "However, the characteristics and clinical outcomes of advanced SMARCA4‐deficient thoracic tumors, particularly in response to immunotherapy, remain underexplored." (PMID 38124509, 2023). "Inactivating mutations and loss of expression of SMARCA4 have been implicated in thoracic tumors." (PMID 37115272, 2023). "A SMARCA4-deficient undifferentiated thoracic tumor presents as undifferentiated round cells or rhabdoid cells with diffuse positivity for some synaptophysin, extensive necrosis, high mitosis, and high Ki-67 rates, therefore need to be differentiated from LCNEC." (PMID 36304941, 2022). "Although the optimal treatment for SMARCA4-deficient thoracic tumours remains unclear, existing studies indicate a favourable response of these tumours to immune checkpoint inhibitors (ICIs)." (PMID 32995013, 2020). "The 5th edition of the WHO classification of thoracic tumors recognized SMARCA4-deficient undifferentiated tumors as a distinct entity, characterizing them as malignant neoplasms with an undifferentiated or rhabdoid phenotype resulting from SMARCA4 (BRG1) deficiency." (PMID 40291911, 2025). "In addition, SMARCA4-deficient undifferentiated thoracic tumor lacks SMARCA4." (PMID 36304941, 2022). "Our findings underscore the critical importance of identifying SMARCA4 alterations across diverse tumor types, not only in thoracic neoplasms but also in gastrointestinal, gynecologic, and soft tissue malignancies." (PMID 40867304, 2025). "In 2021, SMARCA4-DTS was recognized as a subgroup of NSCLC in the fifth edition of the WHO classification of thoracic tumors." (PMID 41142791, 2025). "According to the 2021 WHO classification of thoracic tumors, SMARCA4-UT is classified under “other tumors of epithelial origin of the lung”." (PMID 40661782, 2025).
thoracic tumors (continued). "SMARCA4-UT typically present as a large central thoracic tumor involving the pulmonary hilum and/or mediastinum in young to middle-aged smokers." (PMID 38180245, 2024). "SMARCA4-deficient undifferentiated tumor (SMARCA4-dUT) is a devastating subtype of thoracic tumor with SMARCA4 inactivation and is characterized by rapid progression, poor prognosis, and high risk of postoperative recurrence." (PMID 38881888, 2024). "In the setting of thoracic neoplasms, it has been described that SMARCA4 loss correlates with poorer outcome and expression of SOX2, CD34, and SALL4, and SMARCB1 loss is mainly seen in thoracic neoplasms of a mesenchymal lineage." (PMID 39125735, 2024). "SMARCA4-UT represents a rare subset of highly aggressive, poorly differentiated thoracic tumors primarily observed in middle-aged individuals with a history of smoking." (PMID 38265099, 2024). "They concluded that SMARCA4-UT exhibited a worse prognosis than undifferentiated thoracic tumors that retained SMARCA4." (PMID 37115343, 2023). "The median survival time and 2-year survival rate were significantly lower in patients with SMARCA4-UT than in patients with undifferentiated thoracic tumors that retained SMARCA4 (mOS: 4 vs 39.9 months; 2-year survival rate: 12.5% vs 64.4%)." (PMID 37115343, 2023). "We studied the immune landscape of 11 SMARCA4-UT samples (total of 9 patients), including 4 primary thoracic tumors (2 biopsies and 2 surgical specimens) and 7 distant metastases: bone (n = 1), lymph node (n = 4), brain (n = 1), and jaw (n = 1)." (PMID 35278076, 2022). "The tumour was called ‘SMARACA4‐deficient thoracic sarcoma’ (SMARCA4‐DTS) until recently, but the currently recommended terminology is SMARCA4‐UT according to the 2021 World Health Organization (WHO) classification of thoracic tumours." (PMID 35822082, 2022). "We expect the present case helps nuclear medicine physicians to widely recognize this new disease and include SMARCA4-DTT as the differential diagnosis when encountering a [18F]FDG-avid aggressive thoracic tumor in heavy smoker men with emphysema." (PMID 34181162, 2021). "These tumors, initially classified as SMARCA4‐deficient thoracic sarcomas or nonsmall cell lung carcinomas (NSCLC), are now formally recognized in the fifth edition of the WHO Classification of Thoracic Tumors." (PMID 41577374, 2026). "The name was changed to SMARCA4-UT in the 2021 WHO Classification of Thoracic Tumors." (PMID 37115343, 2023). "SMARCA4-UT is a recently reported very rare type of thoracic tumor." (PMID 37115343, 2023). "SMARCA4-deficient tumors can be divided into NSCLC and undifferentiated thoracic tumors." (PMID 34440689, 2021). "SMARCA4 (switch/sucrose non-fermentable-related, matrix-associated, actin-dependent regulator of chromatin, subfamily A, member 4)-deficient thoracic tumours have shown poor prognosis in clinical settings." (PMID 32995013, 2020). "However, the difference in OS between PD‐1‐inhibitor‐based therapy and chemotherapy for advanced SMARCA4‐deficient thoracic tumors was not statistically significant (p = 0.105)." (PMID 38124509, 2023). "Whether the new terminology “SMARCA4-DUT,” used by WHO in 2021 in thoracic tumors, applies equally to gastric carcinoma still needs more in-depth studies with larger samples." (PMID 36464671, 2022). "Typical immunohistochemical features for SMARCA4-deficient undifferentiated thoracic tumor is the lack of claudin 4 expression and low or absent keratin immunostaining, in addition to the loss of SMARCA4 (BRG-1)." (PMID 33968782, 2021).
sarcoma (40 papers, 2017 to 2025). A usually aggressive malignant neoplasm of the soft tissue or bone. "The SMARCA4-deficient carcinosarcoma reported in this study is an unclassified pleomorphic sarcoma, which is immunoreactive to the stromal marker Vimentin but non-immunoreactive to the epithelial markers CK, EMA." (PMID 41170461, 2025). "A CT-guided core needle biopsy targeting the central region of the pleura mass (puncture site) yielded necrotic debris without viable tumor cells, consistent with the high central necrosis rate (30–45%) in SMARCA4-deficient sarcomas." (PMID 40978036, 2025). "With the increasing application of DNA sequencing, it’s expected that the diagnosis of SMARCA4-deficient sarcomas will become more frequent in the forthcoming period." (PMID 39439958, 2024). "The SMARCA4-deficient sarcoma is a simple genomic sarcoma with a low mutational burden, characterized by a biallelic inactivation of the SMARCA4 gene with few other genomic alterations." (PMID 39064514, 2024). "Several SMARCA4-deficient poorly differentiated and undifferentiated carcinomas/sarcomas delineated primarily based on BRG1 protein loss have been characterized in various anatomical locations." (PMID 36983010, 2023). "Partial responses to PD1/PDL1 blockade have been reported in PDL1-positive SMARCA4-deficient thoracic sarcomas with pembrolizumab, nivolumab and atezolizumab plus bevacizumab combined with CT." (PMID 37190214, 2023). "Herein we report an exceptional example of hybrid HFLT/PHAT showing progression to a rapidly lethal, SMARCA4-deficient sarcoma with epithelioid and rhabdoid features, a previously undescribed phenomenon." (PMID 34389899, 2022). "B cell lymphomas often have activating mutations in EZH2, and some subtypes of sarcomas have mutations in SWI-SNF subunits SMARCB1 (BAF47) or SMARCA4 (BRG1)." (PMID 35852858, 2022). "As with other SMARCA4-deficient sarcomas, the present tumor was highly aggressive, refractory to chemotherapy, and rapidly lethal." (PMID 34389899, 2022). "In the present case, morphologic, immunohistochemical, and molecular- genetic testing clearly established a pre-existing HFLT/PHAT as the precursor lesion for this SMARCA4-deficient sarcoma." (PMID 34389899, 2022). "The thoracic sarcomas carrying inactivation mutations in SMARCA4 are enriched in genes involved in proliferation and stemness compared to unclassified sarcomas." (PMID 34771683, 2021). "In the last five years, the detection of inactivating mutations in SMARCA4 that cause loss of nuclear protein expression has emerged as a differential diagnostic marker between some types of sarcoma and carcinomas sharing similar molecular characteristics." (PMID 34771683, 2021). "SMARCA4-deficient thoracic sarcoma (SMARCA4-DTS) is a recently identified aggressive subtype of sarcoma." (PMID 33866513, 2021). "The final diagnosis was carcinosarcoma with a SMARCA4 deficiency in the sarcoma area; pT4N2M0." (PMID 41170461, 2025). "Through extrapolation, these same therapies may have value in treating the SMARCA4-deficient sarcoma, so future studies are needed to explore this proposition." (PMID 39064514, 2024). "Furthermore, SMARCA4-deficient sarcoma shows a conservation of microsatellite stability (MSS), unlike undifferentiated carcinomas which are more often associated with microsatellite instability (MSI)." (PMID 39064514, 2024). "Although only limited conclusions can be drawn from a single case, the natural history of SMARCA4-deficient sarcoma arising in this unique setting appears to be identical to that of SMARCA4-deficient malignancies elsewhere, with significant potential for adverse patient outcome." (PMID 34389899, 2022).
sarcoma (continued). "Postulating that the partially rhabdoid morphology seen in these cases reflects underlying BAF complex inactivation, they performed a targeted sequencing screen on 18 unclassified sarcomas with partial rhabdoid phenotypes, noting SMARCA4 mutations exclusively in the 6 thoracic tumors of the cohort." (PMID 27732970, 2017). "Since the present case was an undifferentiated tumor that was pathologically difficult to clearly classify as sarcoma or carcinoma, we described it as SMARCA4-DTT." (PMID 34181162, 2021). "Highly expressed SMARCA4 is linked to poor prognosis for cancers including ACC (p = 0.00034), mesothelioma (MESO, p = 0.00017), sarcoma (SARC, p = 0.011), and SKCM (p = 0.037) of TCGA datasets." (PMID 34675941, 2021). "Among sarcomas, biallelic SMARCA4 inactivation is a defining feature of the recently described SMARCA4-deficient undifferentiated uterine sarcoma and sinonasal teratocarcinosarcoma." (PMID 33921435, 2021). "SMARCA4 loss disrupts DNA repair via defective homologous recombination (HR) and mismatch repair (MMR), increasing tumor mutation burden (TMB) by 10–15 mutations/Mb compared to SMARCA4-intact sarcomas." (PMID 40978036, 2025). "In addition to SMARCA4-dNSCC, the clinicoradiologic, morphologic, and/or immunophenotypic features of thoracic SMARCA4-dUT are similar to those of other malignancies including neuroendocrine carcinomas, mesotheliomas, and some sarcomas." (PMID 40909976, 2025). "SMARCA4-UT was initially classified as a subtype of sarcoma." (PMID 39497014, 2024). "Immunohistochemistry revealed SMARCA4 loss in the undifferentiated sarcoma, but not in the HFLT/PHAT." (PMID 34389899, 2022). "Inclusion of other SWI/SNF immunomarkers, such as ARID1A, in the differential diagnostic workup of poorly differentiated sarcoma not fitting well-known subtypes, such as SMARCB1 and SMARCA4-deficient sarcomas, is recommended." (PMID 35125107, 2022). "Evaluation of our synaptophysin results with those reported in the literature in sarcomas/mesenchymal neoplasms showed that synaptophysin is most frequently expressed in CCS, DSRCT, ES, and neoplasms deficient for SMARCB1 and SMARCA4." (PMID 34350470, 2021). "Moreover, in our work, immune deconvolution using an independent transcriptome dataset demonstrated a distinct immune profile between NOS NSCLC and sarcomas regardless of the SMARCA4 mutational status." (PMID 35278076, 2022). "Differential diagnoses for SMARCA4-UT include NUT carcinoma, lymphoma, mediastinal germ-cell tumor, round cell sarcomas, and neuroendocrine carcinoma, as well as various types of sarcomas." (PMID 39723373, 2024). "Several case studies of checkpoint inhibitor therapy in thoracic SMARCA4-deficient sarcomas have emphasised that some patients display exceptional and durable responses to anti-PD-1 blockade, although responses were observed in both PD-L1 positive and negative SMARCA4 tumours." (PMID 35327375, 2022). "Due to low incidence of SMARCA4-UT, which was once defined as a new type of sarcoma, and low detection rate of driver genes, nearly no positive cases of driver genes have been reported so far, so there are few clinical applications." (PMID 38347129, 2024).
sarcoma (continued). "In Case 1, the sarcoma region was negative for the SMARCA4, epithelial markers cytokeratin (CK) and epithelial membrane antigen (EMA), CK, EMA, and SMARCA4 were positively expressed in the adenocarcinoma area, thereby warranting carcinosarcoma diagnosis." (PMID 41170461, 2025).
gastric cancer (39 papers, 2010 to 2026). A primary or metastatic malignant neoplasm involving the stomach. "The median survival for SMARCA4-deficient gastric carcinoma is less than one year from diagnosis, whereas the median survival for SMARCA4-deficient thoracic sarcomas is only six months from diagnosis." (PMID 41312169, 2025). "SMARCA4 mutations occurred in 8% (20/258) of gastric cancers in the TCGA study and 10% (5/50) of gastric cancers in Takeshima’s study." (PMID 38877473, 2024). "SMARCA4 mutations occurred in 8% (20/258) of gastric cancers in a TCGA analysis and 10% (5/50) of gastric cancers in Takeshima’s study." (PMID 38090508, 2023). "Gastric carcinoma with SMARCA4 deficiency can be distinguished by gland architecture of differentiation." (PMID 38090508, 2023). "In contrast, the loss of SMARCA2 and SMARCA4 resulted in worse survival, implicating the essential role of the two subunits in undifferentiated/dedifferentiated gastric carcinoma." (PMID 36464671, 2022). "We report a case of SMARCA4-deficient poorly-to-undifferentiated gastric carcinoma." (PMID 41815546, 2026). "SMARCA4 is associated with progression and poor prognosis in gastric cancer." (PMID 38877473, 2024). "Therefore, our report will aid the diagnosis and classification of SMARCA4-deficient gastric carcinoma." (PMID 38380366, 2024). "SMARCA4-deficient gastric carcinoma has been reported sporadically since 2016." (PMID 38380366, 2024). "Gastric SMARCA4-UT is a rare entity of gastric cancer with a poor prognosis, predominantly occurs in male patients." (PMID 38877473, 2024). "Immunohistochemical staining for SMARCA4 (BRG1) should be performed in gastric cancers with solid architecture and undifferentiated components, especially those with rhabdoid morphology." (PMID 38877473, 2024). "In contrast, other studies have reported tumorigenic effects of SMARCA4 on the development of prostate cancer, gastric cancer, and breast cancer." (PMID 36922568, 2023). "SMARCA4 promotes gastric cancer metastasis by suppressing E-cadherin expression and increasing vimentin expression." (PMID 36902184, 2023). "Inactivation of SMARCA4 is more likely to occur in gastric cancer with a solid and undifferentiated morphology, presenting in large and locally advanced tumors." (PMID 38090508, 2023). "In our study, the expression of SMARCA4 in gastric cancer cells was higher than that in normal cells." (PMID 33987081, 2021). "Especially with regard to a possible determination of SWI/SNF status in routine diagnostics, it seems reasonable to limit the determination of SWI/SNF status in gastric cancer to SMARCA4, SMARCA2, and ARID1A." (PMID 34359794, 2021). "Inactivation of SMARCA4 rarely occurs in classic glandular gastric cancer as a driver molecular event and is more likely to occur in gastric cancer with solid and poorly differentiated and undifferentiated morphology, and loss of SMARCA4 is associated with adverse clinical characteristics." (PMID 38877473, 2024). "When SMARCA4 is mutated in gastric cancer, our data indicated that SMARCA4 does not act as a tumor suppressor, which may be due to the pathological activity of abnormal residual complexes of SWI/SNF." (PMID 33987081, 2021). "For instance, the SWI/SNF complex ATPase SMARCA4 is under the control of ubiquitination-mediated degradation, regulated by the SCFFBW7 E3 ubiquitin ligase complex, inducing gastric cancer metastasis repression." (PMID 36361605, 2022).